KRTAP4-9 (keratin associated protein 4-9)
Description:
In the hair cortex, hair keratin intermediate filaments are embedded in an interfilamentous matrix, consisting of hair keratin-associated proteins (KRTAP), which are essential for the formation of a rigid and resistant hair shaft through their extensive disulfide bond cross-linking with abundant cysteine residues of hair keratins. The matrix proteins include the high-sulfur and high-glycine-tyrosine keratins.
Synonyms: KAP4.9
Tractability: No criterion of Open Targets' tractability assessment is met for any kind of drug.
Gene: Protein-coding gene on chromosome 17 (41,105,389 to 41,106,488, forward strand). Ensembl gene ENSG00000212722.
Pathways (Reactome):
Developmental Biology: Keratinization
Gene Ontology:
Biological process: hair cycle
Cellular component: cytosol; keratin filament
Genetic constraint (gnomAD): Loss-of-function variants: 8 observed, 6.25 expected, observed/expected ratio (o/e) 1.28, 90% interval 0.73 to 1.89. That is too few expected variants to judge how well the gene tolerates losing a copy. Missense variants: 297 observed, 267.02 expected, observed/expected ratio (o/e) 1.11, 90% interval 1.01 to 1.22. Synonymous variants: 111 observed, 86.29 expected, observed/expected ratio (o/e) 1.29, 90% interval 1.1 to 1.51.
Homologues: Orthologues: mouse Krtap5-24 (38% identical), mouse Krtap5-2 (38% identical), mouse Krtap5-26 (36% identical), rat Krtap5-8 (35% identical), rat AABR07006049.1 (33% identical), mouse Krtap5-20 (30% identical). Paralogues in human: KRTAP4-11 (85% identical), KRTAP4-8 (80% identical), KRTAP4-6 (78% identical), KRTAP4-12 (71% identical), KRTAP4-7 (69% identical), KRTAP4-5 (65% identical), KRTAP4-4 (59% identical), KRTAP4-3 (57% identical), KRTAP4-16 (54% identical), KRTAP4-2 (51% identical), KRTAP4-1 (46% identical), KRTAP10-7 (44% identical), and 35 more.